DCTN1 (dynactin subunit 1)
Diseases named in the same sentence as DCTN1 in open-access papers (continued):
Sharing a sentence is not in itself a finding about the gene and the disease.
psychiatric disorder (1 paper, 2020). A disorder characterized by behavioral and/or psychological abnormalities, often accompanied by physical symptoms. "The exon/intron 22 region of the DCTN1 gene, as well as factors that affect splicing efficiency, and alternative splicing, in this region deserve further intense scrutiny in psychiatric disorders." (PMID 32325768, 2020).
DCTN1 also shares sentences with these, for which no sentence is quoted: hereditary spastic paraplegia (3 papers); Alzheimer disease (2); Ataxia (2); Charcot-Marie-Tooth disease (2); distal hereditary motor neuronopathy type 7B (2); distal hereditary motor neuropathy (2); age (1); Anxiety (1); Atrophy (1); brain malformations (1); Charcot-Marie-Tooth disease type 4 (1); chronic gastritis (1); ciliopathy (1); Delusion (1); developmental delays (1); distal motor neuropathy (1); Dystonia (1); focal dystonia (1); gastric adenocarcinoma (1); glioblastoma (1); glioma (1); metastatic cancer (1); muscular dystrophy (1); neurologic disease (1); neuropathy (1); non-small cell lung carcinoma (1); Obesity (1); Onset (1); pancreatic ductal adenocarcinoma (1); renal cell carcinoma (1).
A further 3 diseases each share a sentence with DCTN1 in 1 paper.